SRRM1 (serine and arginine repetitive matrix 1)
Description:
Part of pre- and post-splicing multiprotein mRNP complexes. As a component of the minor spliceosome, involved in the splicing of U12-type introns in pre-mRNAs (Probable). Involved in numerous pre-mRNA processing events. Promotes constitutive and exonic splicing enhancer (ESE)-dependent splicing activation by bridging together sequence-specific (SR family proteins, SFRS4, SFRS5 and TRA2B/SFRS10) and basal snRNP (SNRP70 and SNRPA1) factors of the spliceosome. Stimulates mRNA 3'-end cleavage independently of the formation of an exon junction complex. Binds both pre-mRNA and spliced mRNA 20-25 nt upstream of exon-exon junctions. Binds RNA and DNA with low sequence specificity and has similar preference for either double- or single-stranded nucleic acid substrates.
Synonyms: SRm160; POP101; MGC39488; 160-KD
Tractability: Small molecule: a structure with a bound ligand is known; it has a binding pocket of medium quality. PROTAC: UniProt records ubiquitination sites on it; ubiquitination databases record sites on it; its protein half-life has been measured.
Gene: Protein-coding gene on chromosome 1 (24,631,716 to 24,673,281, forward strand). Ensembl gene ENSG00000133226.
Subcellular location: Nucleus matrix; Nucleus speckle
Subcellular location (Human Protein Atlas): Nuclear speckles
Pathways (Reactome):
Metabolism of RNA: Transport of Mature mRNA derived from an Intron-Containing Transcript; mRNA 3'-end processing; mRNA Splicing - Major Pathway
Signal Transduction: RHOBTB1 GTPase cycle; RHOBTB2 GTPase cycle
Disease: Dengue Virus-Host Interactions
Gene Ontology:
Molecular function: protein binding; RNA binding
Biological process: mRNA splicing, via spliceosome; regulation of mRNA splicing, via spliceosome; RNA splicing; RNA splicing, via transesterification reactions
Cellular component: catalytic step 2 spliceosome; nuclear matrix; nuclear speck; spliceosomal complex; U12-type catalytic step 2 spliceosome; U2-type catalytic step 1 spliceosome; cytosol; nucleoplasm; nucleus
Genetic constraint (gnomAD): Loss-of-function variants: 12 observed, 86.35 expected, observed/expected ratio (o/e) 0.14, 90% interval 0.088 to 0.22. The upper end of that interval is the gene's LOEUF score, 0.22, which puts it in group 1 of 6, group 1 being the genes least tolerant of losing a copy. Missense variants: 843 observed, 1,050.6 expected, observed/expected ratio (o/e) 0.8, 90% interval 0.76 to 0.85. Synonymous variants: 403 observed, 388.8 expected, observed/expected ratio (o/e) 1.04, 90% interval 0.95 to 1.13.
Homologues: Orthologues: chimpanzee SRRM1 (100% identical), macaque SRRM1 (99% identical), dog SRRM1 (98% identical), pig SRRM1 (98% identical), rabbit SRRM1 (97% identical), mouse Srrm1 (96% identical), guinea pig SRRM1 (96% identical), rat Srrm1 (95% identical), tropical clawed frog srrm1 (74% identical), Drosophila melanogaster Srrm1 (34% identical).
Diseases named in the same sentence as SRRM1 in open-access papers:
SRRM1 is named in the same sentence as 12 diseases in open-access papers, as found by Europe PMC text mining. Sharing a sentence is not in itself a finding about the gene and the disease. The quoted sentences say what the papers report.
prostate carcinoma (2 papers, 2022). A carcinoma that arises from epithelial cells of the prostate gland. "Overexpression of SRRM1 has been associated previously with poor prognosis in prostate cancer and silencing of SRRM1 was shown to reduce cell proliferation through a reduction of AKT phosphorylation levels and an increased expression of PTEN, a well-known tumor suppressor." (PMID 36518527, 2022). "One of the genes with the highest predictive value in our risk-prediction signature was SRRM1, which showed the highest correlation with the risk score (Pearson r = 0.51, P-value = 8.18e–30) and has been associated before with poor prognosis in prostate cancer." (PMID 36518527, 2022).
atherosclerosis (1 paper, 2025). A disease characterized by the build-up of fatty material and calcium deposition in the arterial wall resulting in partial or complete occlusion of the arterial lumen. "Of the 25 shared novel atherosclerosis loci with evidence of colocalization, 7 analyses strongly colocalized with PRPA ≥0.80 (nearest gene: BNC2, SCAI, TSC22D2, SRRM1, ABCB11, PRRX2)." (PMID 40313769, 2025).
COVID-19 (1 paper, 2022). A disease caused by infection with severe acute respiratory syndrome coronavirus 2. "While IL6R is is already a therapeutic target for COVID-19, and SRRM1 has been reported in a previous pre-print, these were found in smaller cohorts and will require replication." (PMID 36327219, 2022).
gastric cancer (1 paper, 2025). A primary or metastatic malignant neoplasm involving the stomach. "Comparable high levels of SRRM1 were observed in human gastric mucosal cells GES‐1, gastric cancer cells HGC27, BGC‐823, and nasopharyngeal cancer cells HNE1, CNE1, and CNE2." (PMID 40729735, 2025).
leukemia (1 paper, 2022). A malignant (clonal) hematologic disorder, involving hematopoietic stem cells and characterized by the presence of primitive or atypical myeloid or lymphoid cells in the bone marrow and the blood. "This provides an additional layer of evidence for the potential role of SRRM1 in the progression of leukemia and, in particular, B-ALL." (PMID 36518527, 2022). "SRRM1 has been described as an essential gene, but a knockdown is known to produce a reduction of the cell viability without killing the cell, opening the door to SRRM1 expression modulation as a potential strategy to reduce the aggressive phenotype of leukemia cells." (PMID 36518527, 2022).
nasopharyngeal carcinoma (1 paper, 2025). A carcinoma arising from the nasopharyngeal epithelium. "We demonstrated that targeting the prion‐like domain of EBNA1 inhibits protein aggregates formation, promots SRRM1 alternative splicing and inhibits nasopharyngeal cancer progression." (PMID 40729735, 2025). "Targeting the PrLD of EBNA1 inhibits the formation of protein aggregation, promotes alternative splicing of SRRM1, and inhibits the progression of nasopharyngeal carcinoma." (PMID 40729735, 2025). "We examined SRRM1 protein expression levels in multiple gastric and nasopharyngeal cancer cells by Western blotting." (PMID 40729735, 2025).
tumor (4 papers, 2022 to 2025). "Overexpression of SRRM1(+) significantly promoted the tumor growth in vivo, whereas SRRM1(−) suppressed it." (PMID 40729735, 2025). "EBNA1 condensate interacting molecules are examined and are found that EBNA1 interacts with the splicing factor SRSF1 to regulate alternative splicing of SRRM1 and promote tumor progression." (PMID 40729735, 2025). "EBNA1 interacts with the splicing factor SRSF1 to regulate the expression of the SRRM1 splicing isoforms, thereby promoting EBV‐associated tumor development." (PMID 40729735, 2025). "To further clarify the function of SRRM1 splice isoforms on tumor progression in vivo, we established a tumor growth model by injecting HONE1 cells stably expressing SRRM1(−) or SRRM1(+) into the nude mice." (PMID 40729735, 2025). "Furthermore, EBNA1 interacts with the splicing factor SRSF1 to regulate the alternative splicing of SRRM1 and promote tumor development in vitro and in vivo." (PMID 40729735, 2025). "This leads us to propose that SRRM1 overexpression may contribute to sustaining tumor malignancy and lead to poor prognosis in B-ALL." (PMID 36518527, 2022). "SRRM1, which is overexpressed in HCC tissues, promotes tumor progression by activating the JAK/STAT pathway." (PMID 40303979, 2025).
cancer (2 papers, 2021 to 2022). A tumor composed of atypical neoplastic, often pleomorphic cells that invade other tissues. "Importantly, we analysed data from a recent pan-cancer protein map atlas based on 946 human cancer cell lines, and found that SRRM1 presents the highest protein levels in hematological tumors." (PMID 36518527, 2022). "Transcriptomic analysis of PDAC samples that were screened for homogenous cancer cell population using the Psycomics tool indicated that MEX3A, and to a lesser extent SRRM1, were expressed at significantly higher levels in basal‐like tumors." (PMID 33159833, 2021).
immune disorders (1 paper, 2024). "Additionally, phagosomes were implicated in certain immune disorders, with RPS4Y1, RPS10, SRRM1, and PNN target genes playing roles in the NOD-like receptor signaling pathway." (PMID 38770048, 2024).
SRRM1 also shares sentences with these, for which no sentence is quoted: B-cell acute lymphoblastic leukemia (1 paper); hematological tumors (1); liver cancer (1).